IL6 (interleukin 6)
Diseases named in the same sentence as IL6 in open-access papers (continued):
Sharing a sentence is not in itself a finding about the gene and the disease.
epilepsy (continued). "Notably, both adiponectin and IL-6 are closely related to epilepsy." (PMID 33042001, 2020). "However, there have been conflicting reports regarding the role of IL-6 in seizures and epilepsy." (PMID 29464573, 2018). "Thus, in the search for complementary therapy for epilepsy, this study was conducted to examine the potential anti-inflammatory effects of fish oil supplementation on the levels of the pro-inflammatory cytokine IL-6 in the heart of rats with chronic epilepsy." (PMID 28649227, 2017). "The levels of proinflammatory cytokines such as interleukin 6 (IL-6) and interferon γ in the peripheral blood of the epileptic patients are usually higher than those of control patients, implicating the role of immune factors in the disease process of epilepsy." (PMID 27882059, 2016). "In this paper, differential changes in IL-6 and IL-12p40 related to EEG findings, thereby suggesting that a down-regulated expression of IL-6 in combination with an up-regulated IL-12p40 could be an element related to a risk of epilepsy comorbidity in autism." (PMID 27983615, 2016). "Therefore, the interrelation between IL-6 and epilepsy requires further study." (PMID 24348794, 2014). "Furthermore, IL-6 is closely associated with neurological excitability; thus it has been proposed that IL-6 may be involved in epilepsy." (PMID 24348794, 2014). "Proinflammatory cytokines such as IL-1β, TNF-α and IL-6 have been shown to be overexpressed in experimental models of seizures, prominently by glia, suggesting that glia activation may contribute to vascular inflammation in epilepsy." (PMID 20863362, 2010). "Blood and brain tissues were collected for biochemical assays (SUR1, TRPM4, IL-1β, IL-6, TNF-α, TAS, TOS, OSI, thiol-disulfide homeostasis), histological analyses (H&E, Cresyl Violet, and 8-OHdG immunostaining), and qRT-PCR of epilepsy-related miRNAs." (PMID 41718951, 2026). "Quantitative PCR revealed that IL-1β, IL-6, and TNF-α mRNA levels were markedly elevated in the PBS-treated epilepsy group but significantly suppressed in the L. eligens-treated epilepsy group." (PMID 41356796, 2026). "Previous studies in epilepsy patients treated with VNS have shown that incubating whole blood with endotoxin results in a significantly reduced release of TNF‐α, IL‐1β, and IL‐6 4 h post‐VNS." (PMID 39903575, 2025). "Notably, AKT1, INS, and IL-6 emerged as central nodes, which were functionally associated with lipid metabolic and inflammation processes, particularly glycerophospholipid metabolism, suggesting their potential as key therapeutic targets of XYC for epilepsy treatment." (PMID 40880740, 2025). "A previous study involving 145 poststroke epilepsy patients compared a LTG plus VPA treatment group and a VPA-only group in terms of the serum HMGB-1, matrix metalloproteinase (MMP)-9, and IL-6 levels." (PMID 40806813, 2025). "Hidradenitis suppurativa (HS) is the main pathology of cognitive and functional disorders mainly related to epilepsy, primarily temporal epilepsy, with the release of IL-1b, TNF, and IL-6." (PMID 39166055, 2024). "Even in epilepsy, HS is the main pathology of cognitive and functional disorders that are specifically related to TLE, releasingIL-1b, TNF, and IL-6." (PMID 39166055, 2024). "To ascertain the involvement of neuroinflammation in the therapeutic mechanism of Gent-treated epilepsy seizures in mice, we conducted an evaluation of the protein levels of IL-1β, TNF-α, and IL-6 in hippocampi using Western blot analysis." (PMID 39598325, 2024). "Extensive research has confirmed that excessive activation of astrocytes and the subsequent release of various pro-inflammatory cytokines, such as IL-1β, IL-6 and TNF-α, are considerably involved in the pathogenesis and progression of epilepsy." (PMID 39598325, 2024).
epilepsy (continued). "In clinical studies, an increase in the content of proinflammatory cytokines IL-1β, interleukin-6 (IL-6), and tumor necrosis factor-α (TNF-α) was found in the cerebrospinal fluid of patients with epilepsy after an epileptic seizure." (PMID 37047481, 2023). "It is also important to consider that IL-6 production is triggered by acute epileptic seizures, increasing the likelihood that they may be causal rather than the consequence of autoimmune aspects of epilepsy." (PMID 37025699, 2023). "We used two models of neuronal hyperactivity [an epilepsy model induced by KA, and a model of traumatic brain injury (TBI)] and different models of inflammation (LPS, Poly I:C, IFN-α and IL-6)." (PMID 37496737, 2023). "By regulating miR-203, UCA1 decreases IL-1β, IL-6, TNF-α, and Cox-2 levels via miR-499b-5p in epilepsy." (PMID 35898503, 2022). "Elevated levels of IL-6 and an overall higher oxidative stress index was observed in these patients compared to healthy controls or patients with ‘well-controlled’ epilepsy, potentially indicating that IL-6 might be a good prognostics marker for drug-resistant epilepsy." (PMID 35052661, 2022). "Meanwhile, NEAT1 promotes IL-6, cyclooxygenase (COX)-2, and TNF-α expression by targeting miR-129-5p and activating the Notch signaling pathway in epilepsy." (PMID 35898503, 2022). "In murine models of inflammation, LTG significantly inhibited IL-1β, IL-6, and TNF-α secretion in vivo and in vitro, revealing possible immunomodulatory properties of LTG in epilepsy and BD." (PMID 34791253, 2022). "The use of anti-IL-1, anti-IL-6, and anti-CD20 agents in patients with drug-resistant epilepsy and refractory status epilepticus has shown promising results and a good safety profile." (PMID 35359659, 2022). "The most commonly studied IL-1β, IL-6, and TNF-α tend to be potential mediators in the neuropathology of epilepsy." (PMID 34976232, 2021). "Elevated expression of IL-1, IL-6, and INF-α in epileptic foci demonstrates that inflammation is indeed closely related to the occurrence and development of epilepsy." (PMID 33776649, 2021). "LncRNA NEAT1 promoted IL-6, COX-2, and TNF-α expression by targeting miR-129-5p and activating the Notch signaling pathway in epilepsy." (PMID 33776905, 2021). "In line with the role ofinflammatory agents in epilepsy, the induction of IL1α, TNF-α, and IL-6 has been shown in both neuronsand glia before epilepsy onset." (PMID 33650824, 2021). "LncRNA UCA1 was downregulated in epilepsy, whereas the UCA1/miR-203/MEF2C axis inhibited the activation of NF-κB signaling pathway and IL-6, TNF-α, and Cox-2 levels in epilepsy." (PMID 33776905, 2021). "The levels of several pro-inflammatory cytokines such as IL-1β, IL-6, and TNF-α are often elevated in cerebrospinal fluid and serum of patients or rats with epilepsy." (PMID 34924959, 2021). "Recently, we also showed that IL-6 is increased in the plasma of TLE patients compared to extra-temporal lobe epilepsy (XLE) patients, suggesting that the epilepsy type is a major factor in the seizure-induced production of IL-6." (PMID 32532251, 2020). "The epilepsy group which presented generalized seizures also demonstrated a positive correlation between IL-1β vs. CASP1 and IL-6 vs. CASP3." (PMID 32219137, 2020). "Numerous studies have shown upregulation of IL-1β, IL-6, and TNF-α in animals with (recurrent) seizures and patients with epilepsy." (PMID 33324329, 2020). "Serum α-synuclein did not showed significant correlation with serum levels of IFN-β, IFN-γ, IL-1β, IL-6, IL-10 and TNF-α in patients with epilepsy and acquired demyelinating disorders of the CNS." (PMID 32151248, 2020). "In the pilocarpine model of epilepsy, proinflammatory cytokines in the blood of omega-3 fatty acid-treated rats, including IL-1ß, TNF-α, and IL-6,all decreased, supporting the anti-inflammatory role of n-3 PUFAs in epilepsy." (PMID 31185666, 2019).
epilepsy (continued). "In the context of epilepsy, microglia and astrocyte activation is routinely observed in the epileptic brain foci from patients, alongside elevated levels of CX3CR1, IL-6 and TNF-α." (PMID 31717556, 2019). "In the central nervous system, interleukin (IL)‐1β, IL‐6 and tumour necrosis factor (TNF)‐α have a regulatory role in pathophysiological processes of epilepsy." (PMID 31144434, 2019). "Serum IL-6, IL-1β, TNF-α, and MIP-1α levels were elevated in AED-resistant epilepsy patients and, in patients undergoing resection of the epileptogenic region, IL-1β, TNF-α, and MIP-1α levels decreased after 8 weeks postoperatively." (PMID 27737716, 2016). "IL-1beta, IL-8, IL-12p70 and MIP-1beta were significantly increased in the epileptogenic cortex; IL-6 and MCP-1 were significantly higher in patients with family history of epilepsy." (PMID 20021679, 2009). "We found significantly higher IL-6 and MCP-1 level in our small number of patients with a family history of epilepsy." (PMID 20021679, 2009). "Our results proved that XYC exerted favorable effect on epilepsy by modulating the gut microbiota and serum lipid metabolic, especially neuroinflammation and glycerophospholipid metabolism by regulating the AKT1, INS and IL-6 expression levels." (PMID 40880740, 2025). "Proinflammatory factors, such as IL‐1β, IL‐6, TNF‐α, and TGF‐β, were reported to play important roles in epileptogenesis, indicating that inflammatory response in the brain is a crucial mechanism in the pathophysiology of epilepsy." (PMID 38357846, 2024). "Inflammatory mediators, such as cyclooxygenase-2 and nuclear factor κB (NF-κB), along with inflammatory factors like interleukin-1β, IL-6, tumor necrosis factor (TNF) -α, and prostaglandin E2 (PGE2), play a significant role in the occurrence and progression of epilepsy." (PMID 39121110, 2024). "Omrani and colleagues found that EPA and DHA supplementation in patients with refractory epilepsy experienced decreased seizures as well as TNF-alpha and IL-6 concentrations, suggesting a mechanistic commonality between ASD and epilepsy that can be targeted using PUFA supplementation." (PMID 38398876, 2024). "Therefore, we further investigated the levels of serum biomarkers, including SIRT3, IL-6, IL-1β, TNF-α, and CRP in epilepsy patients." (PMID 39091611, 2024). "Senescent‐like microglia in aged animals demonstrate elevated transcript levels for a range of SASPs, including IL‐10, IL1B, IL‐6, TNFA, and BDNF, all of which may contribute to epilepsy and seizure vulnerability." (PMID 39031751, 2024). "The purpose of this study was to analyses the IL-6 and IL-10 concentrations, including the IL6/IL10 ratio, with regard to GADA titers in the same patient cohort that was previously evaluated for the clinical significance of GAD antibodies in epilepsy." (PMID 37025699, 2023). "Children with ASD that also suffered from epilepsy had lower peripheral IL-6 levels compared to ASD children without epilepsy." (PMID 35492721, 2022). "Furthermore, targeting at the inflammatory mediators in epilepsy, anti-IL-1, anti-IL-6, and anti-CD20 agents have been used in patients with drug-resistant epilepsy and refractory status epilepticus, with promising results and a good safety profile." (PMID 36278003, 2022). "Higher levels of IL-12 p40 were found in autistic patients with history of epilepsy, while IL-6 levels were higher in patients without epilepsy." (PMID 35328471, 2022). "Furthermore, we also observed increased plasma IL-6 levels in patients with TLE compared to patients with extra-TLE, suggesting that the epilepsy type is important for determining seizure-induced IL-6 production." (PMID 34215817, 2021). "This may be attributed to the reciprocal effects of epilepsy and PSD on these cytokines as clear from the decrease obtained in TNF-α during the chronic phase of the pilocarpine model and the increase in TNF-α, IL-6, and IL-1β in PSD animals." (PMID 33643575, 2021).
epilepsy (continued). "Serum levels of IFN-γ, IL-1β, IL-6 and IL-10 showed negative correlation with age of disease onset in pediatric epilepsy patients, suggesting that younger patients demonstrated higher inflammatory responses to afebrile seizure attacks." (PMID 32151248, 2020). "Moreover, after tonic–clonic seizures, in vivo studies indicated an elevated production and secretion of proinflammatory cytokines like IL-1β, IL-6, and TNF-α in cerebral spinal fluid (CSF) and blood serum in patients with epilepsy." (PMID 30922332, 2019). "The serum and gene expression of the inflammatory cytokines—IL-1α, IL-1β, IL-2, IL-6, IL-8 and TNF-α—showed the highest levels among the “Epilepsy-only” group followed by lower levels in the epilepsy–cannabis users and finally the lowest levels in the healthy controls." (PMID 31757102, 2019). "Interleukin 6 (IL-6) levels in cerebrospinal fluid (CSF) and plasma from epilepsy patients were significantly increased 24 h post tonic-clonic seizures, and in patients with TLE serum levels of IL-6 and IL-β1 remain upregulated, indicating a chronic immune mechanism." (PMID 29593494, 2018). "Although there were no overall differences in IL-6 between brain regions, there was a significant epilepsy × repeated measures brain region interaction (p < 0.02)." (PMID 27737716, 2016). "A higher IL-6 level was observed in patients without history of epilepsy with interictalepileptiform activity in the frontal brain region, p < 0.05." (PMID 27983615, 2016). "In addition, both IL-6 and CCL2 are elevated in the temporal cortex of pediatric patients from families with epilepsy history." (PMID 26626560, 2015). "Previous research has reported that seizure induces the generation of cytokines, such as interleukin (IL)-1β, IL-6, and tumor necrosis factor (TNF)-α, and that the interactions among these cytokines are related to the development of epilepsy and play a crucial role in epileptogenesis." (PMID 24381640, 2013). "For instance, a rapid activation of proinflammatory cytokines such as IL-1β, IL-6 and TNF-α was observed both in animal models of acquired epilepsy and in brain tissue obtained from patients with temporal lobe epilepsy or cortical developmental malformations undergoing epilepsy surgery." (PMID 39239395, 2024). "In addition, serum SIRT3 levels were negatively correlated with the inflammatory factors IL-6 (Pearson’s correlation −0.221, P = 0.002) and NHS score (Pearson’s correlation −0.272, P < 0.001) of epilepsy patients, while positively correlated with MOCA scores (Pearson’s correlation 0.166, P = 0.018)." (PMID 39091611, 2024). "Interleukin-6 and IL-10 concentrations were measured by ELISA in plasma, and the IL-6/IL-10 ratio was calculated in a cross-sectional cohort of 247 patients with epilepsy who had their GADA titers measured previously for their clinical significance in epilepsy." (PMID 37025699, 2023). "The present study assessed the relationship between levels of the soluble cytokines IL-6 and IL-10, including the IL6/IL10 ratio and GADA titers, in patients with DRE in the same population that had GADA titers measured previously to evaluate their clinical significance in epilepsy." (PMID 37025699, 2023). "Therefore, we used the cytokines IL-1β, IL-18, and IL-6, which are all commonly found in neuroinflammation as inflammatory markers to explore the effect of treatment with GPR120-AAV-KD and GPR120-AAV-OE on neuroinflammation in epilepsy." (PMID 35624482, 2022). "However, epilepsy in patients with NIND does not result in a high level of CSF IL-17A or IL-6 as compared to immune-mediated epilepsy in the elderly." (PMID 34054854, 2021). "During our previous analyses with IL-6 in TLE or XLE patients, we could not detect such association with epilepsy duration." (PMID 32532251, 2020).
epilepsy (continued). "The brain tissue of patients with epilepsy undergoing surgical resection exhibits a strong inflammatory response, including reactive astrocyte proliferation, the infiltration of activated microglia, and the upregulation of various pro-inflammatory factors, including Cox-2, IL- 1β, TNF-α, and IL-6." (PMID 30983975, 2019). "However, it is important to note that IL-6’s effects on epilepsy are not all harmful." (PMID 41306289, 2025). "Finally, Wang, Wang found that in three distinct types of epilepsy, namely temporal lobe epilepsy (TLE), extra-temporal lobe epilepsy (XLE), and idiopathic generalized epilepsy (IGE), only four independent cytokine biomarkers (IL-6, IFN-γ, IL-17-a, and IFN-λ3) are correlated with severe seizures." (PMID 39861097, 2024). "Indeed, inflammatory mediators may be relevant for the pathogenesis of epilepsy in FCD, as confirmed by the reported up-regulation of inflammatory cytokines and their receptors and/or downstream effectors (such as IL-1β, IL-6, CCL3, CCL4, STAT3, C-JUN and CCR5) in this disease." (PMID 35741692, 2022). "Therefore, the present non-significant changes in IL-6 and IL-1β may be due to an adaptive mechanism in the chronic state of pilocarpine-induced epilepsy." (PMID 33643575, 2021). "The contents of IL-6 and TNF-α in serum of EP + miR-103a inhibitors group was significantly lower than that in the EP + inhibitors NC group (P < 0.05), indicating that the interference of miR-103a expression could reduce the inflammatory damage in epilepsy rats." (PMID 31049031, 2019). "Regardless of the role of the inflammatory system in epilepsy, it will be important to pursue the anticonvulsant and antiepileptogenic effects of the antagonists of shared mediators of inflammation and synaptic plasticity, including cyclooxygenase products, IL-1β, IL-6, and TNFα." (PMID 26464976, 2015). "Elevated concentrations of interleukin-6 (IL-6), interferon-gamma (IFN-γ), and interleukin-17A (IL-17A) have been observed in the plasma during the interictal phase of epilepsy, whereas IL-1β, TNF-α, and IL-10 did not rise in comparison to a healthy group." (PMID 39861097, 2024). "During epileptogenesis and the chronic phase of epilepsy, the hippocampal concentrations of TFN-α and IL-1β increase on days 8, 18, and 28 post-SE, while the IL-6 concentration did not change at any of these three evaluation times." (PMID 37047461, 2023). "In the present study, although TPM was able to induce the recovery of the IL-6 levels, the difference between the IL-6 levels in the TPM and epilepsy groups was not significant." (PMID 24348794, 2014). "Interestingly, IL-2 and IL-10 had high variability across all tissues independent of epilepsy status, whereas VEGF, IL-6, and IL-8 showed greater variability in epileptic compared to nonepileptic tissues." (PMID 27737716, 2016). "In addition, the TPM group (2.18±0.56) had a different recovery rate; however, the difference in IL-6 expression was not significant between the TPM and epilepsy groups (P>0.05)." (PMID 24348794, 2014). "In fact, IL-6, IL-1β, and MIP-1α levels were higher in the temporal cortex than in the hippocampus, and TNF-α showed no regional or epilepsy-related differences, though levels in entorhinal cortex may have been lower than either the hippocampus or temporal cortex." (PMID 27737716, 2016).